GCG (glucagon)
Diseases named in the same sentence as GCG in open-access papers (continued):
Sharing a sentence is not in itself a finding about the gene and the disease.
diabetes (continued). "Similarly, researchers studying diabetes therapies may employ stains to detect insulin- or glucagon-positive cells within explanted devices [21,]." (PMID 40547419, 2025). "The palette model of diabetes posits that individuals develop T2D due to defects in multiple etiological pathways, including, but not limited to, beta cell function, beta cell mass, insulin action, glucagon secretion/action, incretin secretion/action, and fat distribution." (PMID 39859351, 2025). "The significance of proglucagon-derived peptides, such as GLP-1 and GLP-2, in the regulation of metabolism and feeding is well recognized; however, the roles of specific proglucagon proteoforms in the pathophysiology of diabetes are still largely underexplored." (PMID 40056450, 2025). "Notably, elevated glucagon responses have also been observed in individuals with subtle impairments in glucose metabolism who do not meet the diagnostic criteria for diabetes, such as during an oral glucose tolerance test (OGTT)." (PMID 41149695, 2025). "From this finding, we could say that adropin may affect glucagon release in diabetes mellitus." (PMID 39337311, 2024). "Additionally, AM TCRs did not mimic diabetes-associated proteins such as insulin, the insulin receptor, glucagon, or the glucagon receptor." (PMID 38339075, 2024). "Indeed, the study of glucagon has direct clinical implications for the treatment of diabetes." (PMID 38681771, 2024). "However, in diabetes mellitus, there is dramatic excess of glucagon release by α-cells, attributed to β-cell dysfunction, as well as a lack of suppression of glucagon secretion, thus contributing to increased hepatic glucose production, consequently causing hyperglycemia." (PMID 39337311, 2024). "This evidence map summarizes clinical and nonclinical studies that investigated the metabolic interrelationship of glucagon levels, AA metabolism and liver fat content in a three-way association, the so-called liver-alpha cell axis, in patients without diabetes." (PMID 39459592, 2024). "In patients with diabetes aged 30–70 years, consuming two meals per day, that is, breakfast and lunch, was found to be a more effective strategy for managing fasting plasma glucose, C-peptide, glucagon, and insulin sensitivity levels than consuming six meals per day." (PMID 37165359, 2023). "Furthermore, a significant presence of insulin and glucagon double‐positive cells was detected in islets of db/db mice compared to the lean control, further supporting beta cell dedifferentiation and upregulation of the alpha cell program in diabetes." (PMID 37933577, 2023). "Thus, glucagon is an emergency product in diabetes to prevent hypoglycemia." (PMID 38093651, 2023). "The biological activity of glucagon has recently been proposed to both stimulate hepatic glucose production and also include a paradoxical insulinotropic effect, which could suggest a new role of glucagon in the pathophysiology type 2 diabetes mellitus (T2DM)." (PMID 37635984, 2023). "Furthermore, we found that impairment of Gls2 expression in pancreatic β-cells during hyperglycaemia resulted in the development of significant diabetes mellitus via impairment of insulin increase along with a paradoxical increase in glucagon despite the high plasma glucose." (PMID 37147373, 2023). "To this end, we observed a phenomenon where half of all type 1 diabetes donors showed a significant negative association between RAGE and GCG fluorescent intensities in single islets (4 of 8 type 1 diabetes donors), whereas this was not seen in the absence of diabetes." (PMID 37558746, 2023). "Although the serum glucagon level does not always coincide with the presence of diabetes, it is possible to explain how excessive amounts of glucagon may cause a malfunction of glucose metabolism." (PMID 37628857, 2023).
diabetes (continued). "Therefore, glucagon hypersecretion in diabetes could be a result of enhanced retrograde trafficking of glucagon and Stmn2 from the late endosome toward the TGN, and then through the regulated secretory pathway." (PMID 34923907, 2022). "However, without taking glucagon into account, implications of the overall metabolic state in diabetes risk will undoubtedly be overlooked." (PMID 36056607, 2022). "Subjects with diabetes often exhibit hyperinsulinemia, glucagon dysregulation, hyperglycemia-induced microinflammation, oxidative stress, endoplasmic reticulum (ER) stress, and/or dyslipidemia, which might regulate the SerpinB1 expression via hepatic regulation of FoxO1." (PMID 36331940, 2022). "Moreover, we have also previously shown that sustained administration of desHis1Pro4Glu9-glucagon, or its Lys12 acylated counterpart, can reverse aspects of genetically induced and dietary-induced obesity-related diabetes in obese-diabetic (ob/ob) and high-fat-fed (HFF) mice, respectively." (PMID 36005280, 2022). "Hence, the inhibitory effect of amylin on glucagon secretion in rodents could be translated to diabetes treatment and lead to the approval of pramlintide (Symlin®) as antidiabetic drug." (PMID 35456307, 2022). "Diabetes mellitus (DM) is an endocrinological disorder characterized by a state of hyperglycaemia due to insulin resistance, insulin insufficiency, or excessive glucagon secretion." (PMID 36569667, 2022). "Subsequent experiments in αTC1-6 cells grown in high-glucose media to mimic diabetes unexpectedly showed that inhibition of lysosomal biogenesis decreased glucagon secretion, leading us to hypothesize that glucagon may be secreted through a lysosomal secretory compartment." (PMID 34923907, 2022). "Therefore, proteins within the α-cell secretory pathway are emerging as prominent regulators of glucagon secretion by mediating the intracellular trafficking of glucagon and may explain dysregulated glucagon hypersecretion in diabetes." (PMID 34923907, 2022). "Therefore, we reasoned that diabetes-induced glucagon hypersecretion could occur through a switch from anterograde to retrograde transport." (PMID 34923907, 2022). "IDE deficiency leading to cytoskeleton disarrangements and ciliogenesis impairment in pancreatic α-cells, and most likely in β-cells, results in dysregulation of hormone secretion and cellular immaturity, which maybe triggering insulin and glucagon imbalance seen in diabetes." (PMID 35832432, 2022). "Enhanced glucagon response is proposed to be responsible for increased hepatic glucose production; it is proposed that suppression of hepatic glucagon response may provide therapeutic advantages in diabetes management." (PMID 35211458, 2021). "An additional study found that frequency of SH (loss of consciousness or requirement of glucagon) in the past month was a significant predictor of self-reported post-traumatic stress (PTSD) assessed with the CPTS-RI after adjustment for age and family history of diabetes." (PMID 34855927, 2021). "In addition, counter-regulatory glucagon secretion becomes impaired in both forms of diabetes (particularly T1D), which may result in life-threatening hypoglycemia." (PMID 34787082, 2021). "In addition, as suggested in a previous study, ANP may impact the etiology of diabetes primarily by inhibiting glucagon secretion and the enzyme insulinase produced in the kidneys." (PMID 34663293, 2021). "The dysregulation of intrinsic (intracellular regulation of glucagon/insulin biosynthesis and secretion) and extrinsic (external neurohormonal input that regulates biosynthesis and secretion) mechanisms of glucagon/insulin physiology contribute to the pathogenesis of diabetes." (PMID 35002748, 2021). "Furthermore, we noted an increase in the plasma levels of glucagon in our model of diabetes." (PMID 34295325, 2021).
diabetes (continued). "Therefore, the mechanisms underlying the intrinsic response to glucose may provide potential targets for the control of abnormally up-regulated glucagon secretion in diabetes." (PMID 34659118, 2021). "Thus these findings highlight a central role for delta cells in the context of intra-islet regulation of glucagon secretion, and may have implications for designing drugs for the treatment of hyperglucagonemia of diabetes." (PMID 34659118, 2021). "However, whether circulating AVP contributes to physiological counter-regulatory glucagon release and how this regulation is affected in diabetes remains unknown." (PMID 34787082, 2021). "Indeed, patients with diabetes are characterized by not only a compromised insulin secretion and action but also paradoxically elevated plasma concentrations of glucagon that fail to decline appropriately or even increase in response to an oral glucose tolerance test (OGTT)." (PMID 33270148, 2021). "Therefore, disruptions in the routing of glucagon through the lysosomal pathway may contribute to the hyperglucagonemia of diabetes." (PMID 34659118, 2021). "Finally, patients with diabetes should be made aware of the existence of fast-acting glucagon." (PMID 34638984, 2021). "Thus, somatostatin may represent an attractive approach for treating post-pancreatectomy diabetes by reducing glucagon secretion and improving glucose tolerance." (PMID 33270148, 2021). "Diabetes mellitus (DM) is a heterogeneous group of physiological dysfunctions characterized by hyperglycemia, insulin resistance, insufficient insulin secretion, or glucagon hypersecretion." (PMID 33676437, 2021). "Moreover, as Unger & Cherrington have noted, glucagon excess, rather than insulin deficiency, is the sine qua non condition of diabetes." (PMID 32218947, 2020). "Therefore, controlling excess glucagon secretion may be a potential therapeutic strategy for diabetes so that glycemia and glucose metabolism may be better regulated." (PMID 32117057, 2020). "A signaling pathway that can be initiated by glucose and sodium transport through SGLT-1 or by hydrogen peroxide promotes glucagon secretion and, if overactivated, may induce oxidative stress and ATP reduction as key contributors to glucagon dysregulation in diabetes." (PMID 32774668, 2020). "However, minimizing glucagon production during diabetes could be a good alternative to improve diabetes and prevent the development of insulin resistance." (PMID 33294459, 2020). "Moreover, diabetes is associated with relative glucagon undersecretion at low blood glucose and oversecretion at normal and high blood glucose." (PMID 32774668, 2020). "Diabetes mellitus (DM) is a metabolic disorder characterized by hyperglycemia, which arises from insufficient insulin secretion, insulin resistance, or augmented glucagon production." (PMID 31847392, 2019). "In addition to GLP-1, this class of GPCRs includes receptors for glucagon and GIP, which are intrinsically linked to the pathophysiology or various treatment aspects of diabetes, and GLP-2 receptors that have been identified as the basis for a new treatment for short bowel syndrome." (PMID 31031702, 2019). "These phenomena may partially explain the paradoxical glucagon hypersecretion in diabetes." (PMID 31357734, 2019). "Determining whether glucagon is understood to be a problem in diabetes which needs to be suppressed, or a solution to the global obesity epidemic, is likely to depend on which approach is successfully brought to market first, rather than the relative merits of the two approaches." (PMID 29412829, 2018). "However, in diabetes, this tight coupling is disrupted, resulting in dysfunctional glucagon secretion, which may be a factor in the development of type 2 diabetes." (PMID 30713523, 2018). "Antagonising glucagon action may reduce the associated hyperglycaemia, but may not be beneficial in terms of life expectation of the person with diabetes." (PMID 29412829, 2018).
diabetes (continued). "Thus, additional studies are needed to fully assess whether a pharmacological combination of insulin and glucagon could be beneficial in diabetes treatment." (PMID 29558502, 2018). "In addition, increasing the plasma glucagon concentration and hepatic gluconeogenesis, and enhancing lipolysis in patients with type 2 diabetes mellitus may also prevent hypoglycemia." (PMID 28725273, 2017). "As the glucagon/insulin ratio in terms of biological activity is increased in uncontrolled type 2 diabetes, the glucagon-dependent induction of SLC13A5 expression in liver cells might contribute to hyperlipidemia associated with diabetes." (PMID 28264506, 2017). "Additionally, in Ins2+/− and Ins2−/− mice bearing the Akita-like hProC(A7)Y-CpepGFP transgene, development of diabetes correlated with an increase in the relative intra-islet abundance of immunostainable glucagon-positive cells, and a similar observation was made in Akita islets." (PMID 28702245, 2016). "Lack of blood glucose-lowering insulin after malfunction or autoimmune destruction of the pancreatic β-cells is the recognized cause of diabetes, but recent evidence indicates that diabetic hyperglycaemia would not develop unless lack of insulin was accompanied by hypersecretion of glucagon." (PMID 27044660, 2016). "Furthermore, the role of glucagon has been investigated in the pathophysiology of metabolic disorders, where absence of glucagon action was shown to ameliorate diet-induced obesity and diabetes." (PMID 26378455, 2015). "Insulin producing beta cell and glucagon producing alpha cells are colocalized in pancreatic islets in an arrangement that facilitates the coordinated release of the two principal hormones that regulate glucose homeostasis and prevent both hypoglycemia and diabetes." (PMID 25051960, 2014). "It has very recently been revealed in rats fed a high-fat diet that hypothalamic glucagon signaling can suppress hepatic glucose production, suggesting that hypothalamic glucagon resistance may contribute to the hyperglycemia observed in obesity and diabetes." (PMID 25398139, 2014). "Despite these recent developments the identification of novel substances selectively inhibiting glucagon action is still of great therapeutic interest due to the possibility of direct interference with the crucial pathophysiological mechanisms of hyperglycemia in diabetes." (PMID 23744070, 2013). "Therefore, a strategy involving neutralizing peripheral glucagon actions may be beneficial for hyperglycemia in diabetes." (PMID 23316165, 2012). "Therefore, an approach that suppresses liver glucose production while enhancing intra-islet glucagon actions may present a new therapeutic strategy for diabetes." (PMID 23316165, 2012). "While the idea that AMPK activation may be beneficial in diabetes may seem at odds with the glucagon-stimulating effects of AMPK activation, this must be considered in the context of the activity of upstream AMPK regulators which themselves may be regulated by glucose in α-cells." (PMID 22969729, 2012). "Our results firmly establish that elevated levels of glucagon and increased pancreatic α-cell number are two principle factors in the progression of diabetes and, in fact, compounding the problem, α-cell numbers continue to increase with worsening diabetes in db/db mice." (PMID 21283589, 2011). "Hence the present data strongly suggest that an abnormally increased NO production in α-cells might contribute to the abnormal glucagon hypersecretion in diabetes." (PMID 18478125, 2008). "Even in patients with type 2 diabetes mellitus in the DK/DKA group, a positive correlation was seen between plasma glucagon and serum CPR levels, similar to HHS, and the possibility was suggested that α cell insulin resistance is a cause of hyperglucagonemia." (PMID 41292690, 2026).
diabetes (continued). "In patients with type 2 diabetes mellitus in the DK/DKA group, the plasma glucagon level was positively correlated with plasma glucose, serum osmolality, and serum creatinine, and also positively with serum CPR (ρ = 0.25, P = 0.0429)." (PMID 41292690, 2026). "Tirzepatide, a novel dual glucagon inhibitory peptide (GIP) and glucagon-like peptide-1 (GLP-1) receptor agonist, is used in the management of type 2 diabetes mellitus (T2DM) and chronic weight management." (PMID 41909371, 2026). "A diabetes mellitus (DM) é uma doença metabólica cuja prevalência continua a aumentar e é caracterizada por hiperglicemia resultante da secreção inadequada de insulina, resistência à insulina ou deficiência de glucagon." (PMID 40834212, 2025). "In rodent models of diabetes, administration of exogenous PYY3–36 has resulted in greater glucose-stimulated insulin secretion and suppression of excess glucagon release." (PMID 41228539, 2025). "Type 2 diabetes mellitus (T2DM) is a condition characterized by insulin resistance, inadequate pancreatic insulin secretion, and dysregulated glucagon secretion." (PMID 40012909, 2025). "Diabetes type significantly influenced glucagon knowledge, with T1DM patients being more likely to know about glucagon compared to T2DM patients (p<0.05)." (PMID 40585626, 2025). "The actions of GLP-1 on insulin and glucagon secretion inspired the development of several GLP-1 receptor (GLP-1R) agonists that have revolutionized treatment for obesity and diabetes." (PMID 41178720, 2025). "Unlike other types of diabetes, the dual impairment of alpha and beta cells in type 3c DM alters the interactions between key hormones such as insulin, glucagon, cortisol, catecholamines, and growth hormone, which regulate ketone body production, fatty acid oxidation, and lipolysis." (PMID 39744270, 2024). "The potential efficacy of GABA in hybrid diabetes is relevant given the purported capacity of GABA to increase beta cell mass and reduce glucagon." (PMID 39619323, 2024). "Three diabetes-related therapeutic actions are ascribed to GABA, namely, increasing pancreatic β-cell content, attenuating excess glucagon and tamping down T-cell immune destruction." (PMID 39619323, 2024). "Researchers also found significant increases in norepinephrine, glucagon, and fatty acid binding protein 4 (FABP4) after consuming diets containing propionate, suggesting that propionate may be a “metabolic disruptor” that increases the risk of diabetes and obesity." (PMID 39606109, 2024). "Additionally, the loss of early glucagon response suppression after oral glucose intake is only observed in T2D patients compared to healthy and pre-diabetes individuals, supporting the hypothesis that hyperglycemia in T2D is mainly related to impairment of the early glucagon response." (PMID 39149119, 2024). "An alternative strategy could involve incorporating glucagon or glucagon receptor agonists in conjunction with insulin and GLP-1 receptor agonists, targeting the complex interplay between these hormones and potentially offering benefits for both insulin-deficient diabetes and obesity management." (PMID 38579770, 2024). "The evolving understanding of type 2 diabetes mellitus (T2DM) as a bi-hormonal disorder involving both insulin and glucagon suggests the potential characterization of T2DM as a multi-hormonal disorder with further exploration into the role of NAB cells." (PMID 38371125, 2024). "Type 2 diabetes mellitus (T2DM) is a progressive disease characterized by reduced insulin secretion, increased insulin resistance, and disorders of glucagon metabolism." (PMID 39526249, 2024). "Thus, the combination of impaired secretion of glucagon and non-physiological distribution of injectable insulin contributes to a higher risk of hypoglycaemic events and long-term micro- and macrovascular complications in diabetes patients." (PMID 36404376, 2023).